INS (insulin)
Diseases named in the same sentence as INS in open-access papers (continued):
Sharing a sentence is not in itself a finding about the gene and the disease.
Sepsis (continued). "In light of this, the current Surviving Sepsis Campaign recommends that all patients with severe sepsis who have blood glucose levels that exceed 180mg/dL to be started on intravenous insulin therapy." (PMID 31355098, 2019). "Although insulin therapy has been extensively investigated in critically ill patients, including those with sepsis with mixed results, most studies have targeted glycemic control." (PMID 30646314, 2018). "In the sepsis group, insulin-induced Akt serine phosphorylation in the liver and muscle was blunted when compared with the sham-operated rats, and both atorvastatin and diacerein were able to significantly increase Akt phosphorylation in these tissues." (PMID 29760586, 2018). "Three pioneer randomized controlled trials on tight glucose control found that control of glucose levels with insulin improved the outcome in sepsis patients as compared to control groups." (PMID 29976786, 2018). "It is worth noting that we determined visfatin as nicotinamide phosphoribosyltransferase (NAMPT)—an enzyme form that plays a role in insulin secretion in pancreatic beta-cells, and in the delayed neutrophil apoptosis of sepsis." (PMID 30200554, 2018). "We investigated the effect of these drugs on survival, tissue insulin signaling and inflammatory pathways in the liver and muscle of rats with sepsis induced by cecal ligation and puncture (CLP)." (PMID 29760586, 2018). "Here, we explored the mechanisms by which long‐acting insulin analogue insulin glargine administration, in the context of LPS induced sepsis, contributes to liver injury and glucose metabolism disturbances." (PMID 29285858, 2018). "Our data demonstrated that administration of atorvastatin or diacerein improved insulin sensitivity and disease tolerance during peritoneal-induced sepsis." (PMID 29760586, 2018). "Collectively, these results suggested a POMC‐depended effect of insulin on restoring hepatic GNG in sepsis rats." (PMID 29285858, 2018). "In summary, our work shows that insulin administration displays critical liver and glucose metabolism protective roles in sepsis rat models, possibly through suppression of NF‐κB pathway and neuropeptide POMC‐mediated inhibition of STAT3 in liver." (PMID 29285858, 2018). "Altered circulating levels of insulin, leptin, resistin, and PAI-1 have been previously indicated in acute settings of sepsis and these molecules have been implicated in sepsis pathogenesis." (PMID 29326685, 2017). "Thereby, chemerin is a possible link between systemic inflammation and insulin resistance in sepsis host response." (PMID 26873079, 2016). "Further, we reported, that adiponectin levels and insulin demand were positively correlated during sepsis." (PMID 27601939, 2016). "We prospectively examined 230 patients with severe sepsis and septic shock immediately upon hospital presentation and before any treatment including insulin administration." (PMID 27110221, 2016). "The main precipitating factors of DKA were insulin treatment cessation (87.5%) and infection/sepsis (39.6%)." (PMID 26870116, 2015). "Glucose homeostasis in sepsis is also a complex issue, involving endogenous glucose production, endogenous insulin production, and exogenous substitution of either glucose or insulin." (PMID 26576228, 2015). "In the Efficacy of Volume Substitution and Insulin Therapy in Severe Sepsis study, conducted by the German Competence Network Sepsis, the authors compared 10 % HES 200,000 with lactated Ringer solution as volume replacement therapy in critically ill patients." (PMID 26314293, 2015). "Lcn2, an antimicrobial protein, protects endotoxin-induced sepsis and diet-induced insulin resistance." (PMID 26219821, 2015). "The iNOS-derived NO was required for the development of sepsis-induced skeletal muscle insulin resistance." (PMID 25923657, 2015).
Sepsis (continued). "The therapeutic potential to modify adiponectin in order to improve recovery and insulin-sensitivity during acute sepsis will have to be explored in future studies." (PMID 25580089, 2014). "In the present study, we further investigated the ALI-secondary to sepsis in diabetic rats and the effect of insulin treatment." (PMID 25398720, 2014). "The BAL concentration of PGE2 was also lower in diabetics with sepsis, and increased after insulin treatment." (PMID 25398720, 2014). "The aim of the present study was to investigate the effect of insulin treatment in the ALI secondary to sepsis in diabetic rats." (PMID 25398720, 2014). "In order to simultaneously measure insulin sensitivity and insulin secretion in early sepsis we adapted the endotoxin model to include the FSIVGTT." (PMID 23826335, 2013). "As a result the insulin hypersensitive mice appeared to be protected from LPS and polymicrobial sepsis-induced mortality." (PMID 23825606, 2013). "Our study has demonstrated that critically ill patients have higher serum A-FABP concentrations, which are correlated with markers of sepsis, renal function, tissue perfusion and insulin resistance." (PMID 23375099, 2013). "Sepsis leads to a dysregulated insulin/glucose metabolism with exceedingly high glucose levels contributing to tissue damage and organ failure." (PMID 23825606, 2013). "HOMA-%B based on paired C-peptide, insulin, and glucose levels showed β-cell dysfunction of the pancreas in 38% of hyperglycemic children who were either shock or sepsis survivors." (PMID 21276273, 2011). "These guidelines recommend that patients with severe sepsis/septic shock and blood glucose concentrations ≥ 150 mg/dl receive IV insulin therapy to keep blood glucose levels in the range of 80 - 150 mg/dl." (PMID 21470423, 2011). "The most relevant factors for blood glucose concentrations ≥ 150 mg/dl were age, neurosurgery, severe sepsis/shock as defined by the 1992 definitions, steroids, noradrenaline and insulin." (PMID 21470423, 2011). "With administration of 2.4 mU.kg-1.min-1 insulin, the net release of 3-MH was decreased in sepsis rats (5.25 ± 0.29 vs. 4.3 ± 0.27, P <0.01)." (PMID 21639905, 2011). "After diagnosis of severe sepsis and shock, serum adiponectin levels and hydrocortisone correlated positively with insulin demand, and noradrenaline demand negatively with male adiponectin levels." (PMID 21470423, 2011). "More recently, the volume substitution and insulin therapy in severe sepsis (VISEP) study compared ringer's lactate with HES 200 kDa/0.5 for fluid resuscitation in patients with severe sepsis or septic shock." (PMID 20298543, 2010). "Prior studies have confirmed excessive endogenous insulin secretion during sepsis, which represented an important pathogenetic and prognostic factor in ICU patients." (PMID 20932285, 2010). "The VISEP (Volume substitution and Insulin therapy in severe sepsis) trial assessed the impact of tight glucose control in patients with septic shock or severe sepsis." (PMID 20840773, 2010). "Infants treated with insulin had a higher glucose intake, a higher weight gain, less sepsis and an increased endogenous insulin production." (PMID 20646308, 2010). "In sepsis, the stimulation of eNOS is inhibited and consequently the response of the endothelium on the insulin is limited." (PMID 20003200, 2009). "Resistin (named for resistance to insulin) has been proposed as a novel marker of inflammatory response in sepsis." (PMID 19545363, 2009). "With 537 patients, the recent Efficacy of Volume Substitution and Insulin Therapy in Severe Sepsis (VISEP) trial accounted for approximately half the patients in the review." (PMID 18218122, 2008). "The purpose of this study was to assess the relation between glycaemic control and the severity of sepsis in a cohort of patients treated with intensive insulin therapy (IIT)." (PMID 18939991, 2008).
Sepsis (continued). "At the end of the study, results showed that intensive insulin treatment reduced episode of septicemia by 46%, and overall mortality rate by 32% during their stay in ICU." (PMID 15686591, 2005). "In patients with sepsis and cancer, lower levels of insulin are needed to restore lipid levels than glucose levels." (PMID 15566589, 2004). "She managed IV insulin at home but developed episodes of sepsis and central line blockage." (PMID 41472947, 2026). "Patients with sepsis have elevated insulin levels but decreased insulin sensitivity." (PMID 39891057, 2025). "The immunomodulatory effects of insulin and other anti-diabetic medications may play a protective role in diabetic patients with sepsis, warranting further investigation." (PMID 41321926, 2025). "Overall, these results highlight that patients with T2DM who developed sepsis were older, more obese, had more frequent cardiovascular and renal comorbidities, had higher insulin use, and showed stronger inflammatory and renal dysfunction markers than those without sepsis." (PMID 40863575, 2025). "For example, finetuning the model for distinct clinical scenarios, such as managing sepsis in the ICU or treating patients on the wards with subcutaneous insulin, could broaden its applicability beyond the post-cardiac surgery context." (PMID 40425725, 2025). "Moreover, it improves insulin sensitivity, inhibits platelet aggregation, and reduces mortality in an animal model of sepsis." (PMID 41009650, 2025). "These may include nutritional support (parenteral and enteral), medications (such as postnatal steroids), glycemic interventions (such as insulin administration), intercurrent illnesses (such as sepsis), and fluid or glucose infusion practices." (PMID 41169896, 2025). "Akt activation mediates insulin’s effects on muscle, enhancing glucose uptake, muscle growth, and protein turnover, while also influencing protein metabolism in conditions such as sepsis." (PMID 40725728, 2025). "This may be due to inadequate energy supply, insulin resistance, the accumulation of reactive oxygen species (ROS) and muscle tissue breakdown at the onset of sepsis." (PMID 39498415, 2024). "A possible explanation may be that the aberrant inflammatory response during sepsis is responsible for the metabolic dysregulation that enhances insulin resistance." (PMID 38540711, 2024). "At the same time, composite insulin regimens were introduced shortly after the deterioration of glucose control in a few individuals, especially those with clinical and laboratory signs of severe sepsis." (PMID 38243977, 2024). "In addition, CD4 Th1 T cell abundance was negatively correlated with the insulin signaling pathway (R = -0.72, P < 0.01), with the highest negative correlation, and this pathway was down-regulated in sepsis patients." (PMID 37077915, 2023). "Thus, it is unlikely that either is a substantial contributor to CLP- or sepsis-induced attenuation of insulin activity." (PMID 37550630, 2023). "Thus, sepsis patients often require insulin administration, and insulin can activate mTOR1 which promotes muscle synthesis." (PMID 36902469, 2023). "This is the first report of the widespread ability of representative strains of blood-borne pathogens associated with sepsis to intrinsically bind insulin, regardless of cell wall architecture, i.e., Gram-positive or Gram-negative." (PMID 37998031, 2023). "Changes in insulin resistance during the acute phase of sepsis could reflect the inflammatory state or severity of sepsis." (PMID 37940931, 2023). "Sepsis has long been described as a state of hormonal, and in particular insulin, resistance." (PMID 37550630, 2023). "We found that insulin signaling pathway was down-regulated in sepsis." (PMID 37077915, 2023). "We hypothesize that sepsis attenuates insulin-stimulated tyrosine phosphorylation of either IRβ, IRS-1 or IRS-2." (PMID 37550630, 2023).
Sepsis (continued). "As insulin levels initially decrease during the early phase of sepsis, immunomodulating effects may be mild." (PMID 37144447, 2023). "Otherwise, those parameters were well comparable in the insulin resistance and sepsis group." (PMID 36551906, 2022). "Recently, several ICUAW risk factors have been identified, and therefore we discuss how starvation, insulin resistance, immobilization, inflammation and sepsis, regeneration as well as physiotherapy and mobilization are interrelated with ER stress-induced UPR in muscle." (PMID 35615361, 2022). "High levels of blood glucose are most commonly reported within the first 3 to 5 days of life, as a consequence of limited insulin secretion capacity, increased counter-regulatory hormones, sepsis, parenteral glucose and medications’ administration (e.g. steroids)." (PMID 36619556, 2022). "The 2012 guideline suggested that insulin therapy should be initiated when blood glucose is ≥8.3 mmol/L in general ICU patients; and for patients with sepsis or septic shock, recent guidelines recommended initiating insulin therapy at a blood glucose level of ≥10.0 mmol/L." (PMID 36579147, 2022). "A large nested case–control study analyzing the impact of current treatment with non-insulin agents on the incidence of sepsis demonstrated that metformin may confer a persistent benefit on the rate of hospitalization for sepsis." (PMID 33973089, 2021). "Then, we speculated that RARA-AS1 might be involved in the progression of pediatric sepsis by regulating phagosome, leukocyte transendothelial migration, and insulin signaling pathways." (PMID 33949285, 2021). "Insulin levels are often increased in sepsis patients, while insulin sensitivity is decreased." (PMID 34299201, 2021). "Various factors such as systemic inflammatory response syndrome, sepsis, metabolic crisis, and insulin treatment may influence glucose control in patients with SAH." (PMID 34017305, 2021). "Furthermore, the previous studies revealed that intensive therapy with insulin improved the mortality rate in intensive care units, further indicating that treatment with insulin reduced mortality in patients with sepsis." (PMID 33679687, 2020). "Furthermore, the anti-inflammatory and other immunologic effects, including suppression of excess inflammation and improvement of macrophage function by insulin, have a clinical benefit in improving sepsis outcomes." (PMID 33344465, 2020). "Could insulin be a biomarker of sepsis in newborn like C reactive protein and procalcitonin which are known biomarkers of sepsis." (PMID 32637004, 2020). "Sepsis induces resistance to insulin resulting in little glucose availability for tissues." (PMID 32546181, 2020). "Furthermore, the administration of insulin in mice with LPS-induced sepsis revealed that insulin effectively exerts an anti-inflammatory effect and prevented pyroptosis cell death." (PMID 33679687, 2020). "Babies with asphyxia and sepsis particularly tend to have abnormal serum insulin at admission." (PMID 32637004, 2020). "In support of this hypothesis, we recently found that foals with severe sepsis tend to have lower insulin and GIP concentrations (L.M.R./R.E.T., personal communication)." (PMID 31664736, 2019). "In this study, we demonstrated that peripheral insulin administration could inhibit the activation of hepatic NF‐κB pathway and protect against the liver injury in sepsis rats." (PMID 29285858, 2018). "Atorvastatin and Diacerein may play a critical role in the protection against sepsis through an improvement in the insulin-induced PI3K/Akt pathway." (PMID 29760586, 2018). "As expected, treatment with insulin significantly mitigated injurious changes above in sepsis rats." (PMID 29285858, 2018).
Sepsis (continued). "On the other hand, in the past two decades, adipose tissue has become recognized as a dynamic tissue involved in the regulation of metabolism, the inflammatory response, coagulation, and insulin sensitivity, all of which are major elements in the response to critical illness, particularly to sepsis." (PMID 30301230, 2018). "However, further studies are essential to determine more molecular mechanisms how insulin interacts with POMC neurons to regulate HGP in sepsis." (PMID 29285858, 2018). "This study aimed to investigate whether a statin or diacerein can improve insulin signaling, contribute to disease tolerance and improve survival in sepsis, by reducing inflammatory tissue pathways." (PMID 29760586, 2018). "The PPAR‐γ agonist thiazolidinedione (TZD) was shown to improve peripheral insulin sensitivity and clearance of TGs in type 2 diabetes, while ameliorating murine polymicrobial sepsis by reducing the pro‐inflammatory signal transducer and activator of transcription‐1 (STAT‐1) signaling pathway." (PMID 29976786, 2018). "The aim of the present study was to investigate whether a statin or diacerein can improve insulin signaling, disease tolerance and survival in sepsis by inhibiting inflammatory pathways." (PMID 29760586, 2018). "It is supposed that sepsis patients, who survive the acute phase of the disorder, will suffer from PICS under the suppression of T cell autophagy often caused by nutritional stress, insulin infusion, and sustained inflammation, etc." (PMID 27618275, 2017). "Furthermore, previous studies showed that C5L2 plays an important role in insulin resistance, lipid metabolism and sepsis in a C5L2 KO mice model." (PMID 28052000, 2017). "Whereas both burn injury and sepsis lead to insulin resistance, muscle wasting, and hyperlactatemia, the role of mTORC1 in metabolic alterations may differ between burn injury and sepsis." (PMID 28747716, 2017). "This is surprising since insulin levels are usually normal or slightly suppressed during sepsis." (PMID 28768529, 2017). "Uncoupling protein 2 (UCP2) may be critical for intestinal barrier function which may play a key role in the development of sepsis, and insulin has been reported to have anti-inflammatory effects." (PMID 28428961, 2017). "The ability of insulin to suppress LTB4 and IL-1β production is in tune with the previous suggestion that insulin has anti-inflammatory actions and its infusion may be of benefit in sepsis and ARDS." (PMID 27887602, 2016). "Moreover, we show that myofibroblast differentiation in the lung starts very early after sepsis, is less intense in diabetics and that insulin treatment increases myofibroblast differentiation to the levels of non-diabetics." (PMID 25398720, 2014). "In sepsis models, insulin has been shown to improve immune cell function independently of glycemia." (PMID 25177798, 2014). "Second, we did not evaluate factors that might be related to variability and may influence its effect on outcome, such as intensive insulin therapy, sepsis and organ dysfunction." (PMID 24887049, 2014). "Since insulin suppresses the cytokine formation in response to GBS, peripheral insulin resistance present in newborn infants and particularly during sepsis may promote the inflammatory process." (PMID 25400631, 2014). "As high insulin sensitivity has been shown to have a good performance in ruling out sepsis, FGF21 may be a good tool to exclude sepsis in suspicious cases." (PMID 23999826, 2013). "The negative impact of 10% HES 200/0.5 as compared to modified Ringer's lactate (RL) on renal function in severe septic/septic shock patients was also demonstrated in a recent randomized VISEP (efficacy of fluid substitution and insulin therapy in severe sepsis) trial." (PMID 22277099, 2012). "In our study, we hypothesized than continuous insulin infusion would alleviate degradation of skeletal muscle protein by inhibiting the Ub-proteasome system under sepsis conditions." (PMID 21639905, 2011).